MTOR (mechanistic target of rapamycin kinase)
Diseases named in the same sentence as MTOR in open-access papers (continued):
Sharing a sentence is not in itself a finding about the gene and the disease.
colon carcinoma (continued). "YAP1 was proposed to functioning either partially or in tandem with key oncogenic drivers such as Kras, β-catenin, and Akt/mTOR in colon tumor initiation and progression." (PMID 28241877, 2017). "Here, we showed that hypoxia inhibits translation through activation of PERK and inactivation of mTOR in human colon cancer HCT116 cells." (PMID 27078027, 2016). "To test if BRAF600E mediates ERK activation in colon cancer cells, we overexpressed the mTOR-insensitive and constitutively active form of S6K1 (HAS6K1 E389 delta CT) and mTOR-sensitive WT S6K1 in 600E cells." (PMID 27351224, 2016). "On the other hand, treatments with AKT only inhibitor (GDC0941) or MTOR inhibitor (Rapamycin) reduced cell viability in all three treated mutant BRAF colon cancer cell lines in a similar way." (PMID 26802026, 2016). "In summary, our work identifies EKR-mediated Mcl-1 stabilization via feedback activation of S6K1-IRS-2/PI3K as a novel resistance mechanism to mTOR inhibitors in BRAF600E colon cancer cells." (PMID 27351224, 2016). "In the current study, we identified Mcl-1 upregulation and BRAF600E as resistance mechanisms of mTOR inhibitors in colon cancer cells and in xenografts." (PMID 27351224, 2016). "Stimulation with PDGF can provoke changes in metabolism of colon cancer cells by activation of the PI3K/Akt/mTOR pathway." (PMID 27626684, 2016). "Different molecular pathways are involved in the angiogenesis, but the activation of AkT/mTOR axis has been specifically related to neo-vascularization in the development of inflammation-sustained colon cancer." (PMID 27219328, 2016). "Treatment with PI-103, a PI3K and mTOR inhibitors resulted in a concentration- and time-dependent decrease in PC and Chk-α levels in human prostate and colon carcinoma cell lines." (PMID 26496360, 2015). "The present study suggested that fucoidan exerts an anti-cancer effect on HT-29 human colon cancer cells by downregulating the PI3K-Akt-mTOR signaling pathway." (PMID 25998232, 2015). "Here we extend previous studies of DGKζ-mediated regulation of mTOR by characterizing a functional interrelation of these two proteins in rapamycin-resistant colon cancer cells." (PMID 26302180, 2015). "Consistently, knockdown of TSC2 activates, whereas knockdown of mTOR inhibits, Notch signaling in the human colon cancer cell line LS174T." (PMID 25654764, 2015). "In accordance with our results, decreased levels of miR-424 led to an activated AKT/mTOR pathway in prostate and colon cancer cells." (PMID 25633049, 2015). "Ongoing studies are evaluating agents against the PI3K/mTOR route in combination with anti-EGFR antibodies in colon cancer." (PMID 26418718, 2015). "Our current in vivo findings further expand our earlier in vitro reports in which knockdown of TSC2 inhibited, whereas inhibition of mTOR increased, goblet cell differentiation in colon cancer cells." (PMID 25654764, 2015). "Collectively, these data indicate that phloroglucinol effectively decreases mTOR/p70S6K growth signaling pathways in colon cancer HT-29 cells." (PMID 24970012, 2014). "The positive expression of mTOR and pmTOR was observed to be higher in 75.5% (80/106) and 76.4% (81/106) of the 106 colon cancer specimens, compared with the adjacent normal tissues." (PMID 25120661, 2014). "In this study, we found that GA suppressed the phosphorylation of Akt, mTOR and p70 S6K (a down regulator of mTOR), suggesting the Akt-mTOR pathway is also involved in GA-induced autophagy in colon cancer cells." (PMID 24810758, 2014). "We will also discuss our recent comparative study of diferent mTOR inhibitors in a population of colon cancer stem cells (CSCs), and current major challenges for achieving individualized drug therapy using kinase inhibitors." (PMID 24393708, 2014).
colon carcinoma (continued). "In this study, we detected that the positive rate of mTOR and pmTOR expression was significantly higher in 75.5% (80/106) and 76.4% (81/106) of the 106 colon cancer specimens, compared with the adjacent normal tissues." (PMID 25120661, 2014). "As a positive control rapamycin (an mTOR inhibitor) was used which is well known for inducing autophagic vacuoles in colon cancer cells." (PMID 23533514, 2013). "Here, we demonstrate that the treatment of FC PIK3ca* mice with the mTOR inhibitor, rapamycin, results in a dramatic response in advanced colon cancers." (PMID 23593290, 2013). "We focused on mTOR, since our previous study showed that mTOR inhibition by rapamycin suppresses EMT, invasion and stemness driven by loss of FBXW7 in colon cancer cells." (PMID 24344117, 2013). "Taken together, these results show that ATP-competitive inhibitors of mTOR reduce colon cancer cell proliferation and survival." (PMID 22401294, 2012). "LS174T, SW480 and DLD-1 colon cancer cell lines were treated with PP242 an ATP-competitive inhibitor of mTOR, NVP-BEZ235, a dual PI3K/mTOR inhibitor or rapamycin." (PMID 22401294, 2012). "Taken together, these results show that ATP-competitive inhibitors of mTOR are effective in blocking colon cancer cell growth in vitro and in vivo and thus represent a therapeutic option in colon cancer either alone or in combination with MEK inhibitors." (PMID 22401294, 2012). "Artificial suppression of l-CaD increased susceptibility of colon cancer cells to 5-FU, and caused an increase of p21 and c-PARP, and a decrease of NF-kB and p-mTOR expression." (PMID 23241148, 2012). "Targeting mTOR with allosteric inhibitors of mTOR such as rapamycin reduces colon cancer progression in several experimental models." (PMID 22401294, 2012). "Overall, our study shows that ATP-competitive inhibitors of mTOR efficiently reduced the growth of colon cancer cells both in vitro and in vivo." (PMID 22401294, 2012). "AA005 synergies with glycolysis inhibitor 2-DG for marked ATP generation blockade, and antagonizes cisplatin-induced up-regulation of p-mTOR, leading to enhanced proliferation inhibition and apoptosis induction in colon cancer cells." (PMID 23056575, 2012). "In vivo, the anticancer activity of mTOR inhibitors was evaluated on nude mice bearing colon cancer xenografts." (PMID 22401294, 2012). "In this study, we report that AA005 is able to activate AMPK and inhibit mTOR, therefore arrests cell cycle at G1 phase and induces autophagy of colon cancer cells." (PMID 23056575, 2012). "AA005 also inhibits chemotherapeutic agent cisplatin-triggered up-regulation of mTOR and synergizes with this drug in suppression of proliferation and induction of apoptosis of colon cancer cells." (PMID 23056575, 2012). "Activation of Wnt/β-catenin has been shown to upregulate mTOR activity in colon and uterine cancers, and treatment with an mTOR-specific inhibitor suppresses polyp formation in a colon cancer mouse model." (PMID 21695255, 2011). "HT29 and LS174T colon cancer cells were infected with lentiviruses expressing either a scramble shRNA, raptor shRNA, rictor shRNA or mTOR shRNA." (PMID 20226010, 2010). "To further document the role of mTOR in colon cancer cells, we also treated HT29 and LS174T cells with rapamycin, a chemical inhibitor of mTORC1." (PMID 20226010, 2010). "To gain insight into the mechanism by which rictor and mTOR knockdown reduced colon cancer cell proliferation, we analyzed cell cycle progression using propidium iodide staining and flow cytometry analysis." (PMID 20226010, 2010). "Similarly, PI3K, Akt, and mTOR inhibitors are being evaluated in clinical trials for both gastric and colon cancers." (PMID 40729043, 2025). "An experiment was performed to determine whether the combination of ginger and honey possesses chemopreventive potential in colon cancer cells through the regulation of mTOR, Wnt/β-catenin, and apoptosis signaling pathways." (PMID 40059876, 2025).
colon carcinoma (continued). "Experiments were conducted to evaluate whether the combination of honey and ginger might have chemopreventive potential in colon cancer cells by modulating the apoptosis and Wnt/β-catenin and mTOR signaling pathways." (PMID 40059876, 2025). "Moreover, the apoptosis was induced via a mutant of PI3K/AKT/mTOR signaling cascade in colon cancer HCT-116 cells." (PMID 41180483, 2025). "Based on these findings, we propose that co-targeting ribosome biogenesis and the mTOR signaling pathway may offer a novel therapeutic angle for addressing MDR in colon cancer." (PMID 40724830, 2025). "However, in colon cancer and endometrial cancer cell lines, the increased expression of Sesn2 can inhibit cancer by inhibiting mTOR." (PMID 41614860, 2025). "Likewise, another anticancer drug, cryptotanshinone (CPT), exerts its effects by inhibiting the PI3K/AKT/mTOR pathway in colon cancer." (PMID 41180483, 2025). "Also, for colon cancer a tumor suppressing function was described where a reduced REST expression resulted in enhanced activity of the PI3K/AKT/mTOR signaling pathway, the target of Everolimus, a main therapeutic agent in siNET treatment." (PMID 40410286, 2025). "Additionally, KEGG enrichment analysis linked these genes to critical features, including chemical carcinogenesis of reactive oxygen species, autophagy, and the mTOR signaling pathway, further revealing key molecular events in the development of colon cancer." (PMID 38999959, 2024). "Finally, the apigenin glycoside isovitexin decreased the expression levels of p‐PI3K, p‐Akt, p‐mTOR, and Bcl‐2 and significantly increased the levels of Bax and caspase‐3 in human colon cancer epithelial cells (Zhu, Zhao, and Jiang 2021)." (PMID 39723045, 2024). "For example, rhein inhibits colon cancer cell growth by targeting the mammalian target of rapamycin (mTOR) pathway and human kidney cancer cells through the mitogen-activated protein kinase (MAPK)/nuclear factor kappa-light-chain enhancer of activated B cells (NF-κB) signaling pathway." (PMID 39057925, 2024). "Importantly, an independent analysis of protein arrays of human colon tumors colonized with SGG showed up-regulation of PI3K/Akt/mTOR and MAPK pathways, providing clinical relevance to our findings." (PMID 37696912, 2023). "Additionally, both downregulated the gene expression of PI3K, AKT, and mTOR consequently suppressing colon cancer proliferation by inhibiting the PI3K/AKT/mTOR pathway." (PMID 37493814, 2023). "Additionally, AA has been reported to inhibit cell migration in colon cancer through the PI3K/Akt/mTOR/p70S6K and epithelial–mesenchymal transition (EMT) pathways." (PMID 37375849, 2023). "However, upon treatment with 5-FU or 5-FU nanogel there was an effective reduction in the gene expression of the PI3K, Akt and mTOR confirming the inhibitory potential against the hyperactivated PI3K/Akt/mTOR signaling pathway in colon cancer." (PMID 37493814, 2023). "Indeed, few research groups have studied the anticancer effect of natural C. sinensis polysaccharide inhibiting colon cancer cell proliferation by apoptotic stimulation and autophagy flux blockage via mTOR signaling." (PMID 37114040, 2023). "In addition, reports also suggested that ROS induces apoptotic cell death in colon cancer cells via down-regulating a variety of signaling molecules such as PI3K/AKT/mTOR and up-regulating caspase proteins (Caspase 3 and 9)." (PMID 36737760, 2023). "There is evidence that ERβ may also inhibit colon cancer cell growth through autophagy mediated by suppression of the mammalian target of rapamycin (mTOR) through Cyclin-D1 degradation." (PMID 38137047, 2023). "Importantly, an independent analysis of the protein and phosphoprotein content from human colon tumors enriched for SGG revealed up-regulation of PI3K/Akt/mTOR and MAPK pathways, providing clinical relevance to our findings in the murine model." (PMID 37696912, 2023).
colon carcinoma (continued). "The PI3K/Akt/mTOR signaling pathway and its downstream signaling molecules are directly involved in regulating the proliferation, apoptosis, invasion and metastasis of colon cancer cells." (PMID 36971681, 2023). "Finally, an independent protein analysis of human colon tumors colonized with SGG revealed up-regulation of PI3K/Akt/mTOR and MAPK pathways, providing clinical relevance to our findings in a murine model of CRC." (PMID 37696912, 2023). "In practice, several experimental evidences have documented that high expression of CXCL8 binds to receptors CXCR1 and CXCR2, mediates the transcriptional process of PI3K/Akt/mTOR signaling cascade, and promotes metastasis in multiple malignant tumors, specifically in colon cancer." (PMID 35922850, 2022). "Moreover, active vitamin D3 (VD3) attenuated the expression of the PI3K/Akt/mTOR pathway, inhibited cell proliferation, and promoted apoptosis in colon cancer cell lines." (PMID 35326689, 2022). "Similarly, in the colon cancer model, the combination of vistusertib, an mTOR inhibitor, and anti-CTLA-4, an immune checkpoint blockade, increased the cytotoxic activity of intratumoral CD8+ T cells, by the production of molecules such as IFN-γ and granzyme B." (PMID 36077620, 2022). "A similar finding was reported that meoru anthocyanins, activators of AMPK α1, could prevent colon cancer cell growth by inhibiting mTOR phosphorylation." (PMID 36619198, 2022). "This makes the Notch-Akt-mTOR axis an attractive therapeutic target in colon cancer therapy." (PMID 35335986, 2022). "It presents the link between mTOR dysregulation, chronic inflammation, and colon cancer." (PMID 36293326, 2022). "Additionally, spicatoside A, a Liriope platyphylla-derived compound, induces autophagy and apoptosis of colon cancer cells by down-regulating PI3K/AKT/mTOR." (PMID 36139919, 2022). "Our study further indicates that the potential anti‐cancer effects of Lar in colon cancer may be achieved by activating AMPK/mTOR‐mediated autophagic cell death." (PMID 36251949, 2022). "Fourth, fluoxetine and sertraline could elevate the phosphorylation of AMPK and block downstream mTOR pathway, resulting in autophagic cell death in various cancer cells, and enhance the sensitivity of several chemotherapy drugs on colon cancer cells." (PMID 36497383, 2022). "Similarly, chaetocochin J, a natural alkaloid, promotes apoptosis and autophagy of colon cancer cells by inactivating PI3K/AKT/mTOR and activating AMPK." (PMID 36139919, 2022). "Targeting mTOR inhibited colon cancer growth through the 4EBP1/eIF4E/PUMA pathway." (PMID 36428613, 2022). "We then determined whether mTOR inhibitors and auranofin were cooperatively enhancing ROS levels in gastric and colon cancer cells." (PMID 33754064, 2021). "In particular, the PI3K/mTOR pathway was shown to be one of the mechanisms underlying the resistance of BRAFV600E colon cancer cells to BRAF inhibition that could be overcome by concurrent BRAF and PI3K/mTOR blockade." (PMID 34201061, 2021). "In colon cancer cells, chrysophanol blocks proliferation by inhibiting the mTOR pathway." (PMID 33622177, 2021). "Similarly, high activation of the PI3K/Akt/mTOR pathway in colon cancer stem cells prepared from HT-29 spheroids is induced by insulin and this is accompanied by high expression of PD-L1." (PMID 34163519, 2021). "Because Akt and its downstream target mTOR were activated in serum‐starved CD133‐expressing colon cancer cells, it is possible that the CD133‐Akt‐mTOR regulatory axis positively regulates CD133 production through augmentation of protein synthesis‐related p70‐S6K and 4E‐BP1." (PMID 33720534, 2021).
colon carcinoma (continued). "In BR colon cancer cells, phospho-Akt level increases and results in a decrease in phospho-AMPKα levels and an increase in phospho-mTOR levels, inducing autophagy that protects BR colon cancer cells through the suppression of fatty acid synthesis and developing resistance to butyrate." (PMID 34829834, 2021). "We demonstrated that the novel compound was able to induce apoptosis through intrinsic and extrinsic pathways and was capable of decreasing sICAM-1, mTOR, cathepsin B concentrations, whereas increased Beclin-1 concentration was detected in both colon cancer cell lines." (PMID 33918514, 2021). "Protein expression of the AMPK signaling pathway demonstrated that phospho-AMPKα (Thr172) and phospho-ACC (Ser79) levels significantly increased, whereas phospho-Akt (Ser473) and phospho-mTOR (Ser2448) levels decreased in BR colon cancer cells of HCT116, HT29, and SW480 treated with AICAR." (PMID 34829834, 2021). "Overexpression of PI3K/AKT/mTOR signaling components has been reported in various types of cancer, and is especially closely related to the occurrence, development, and prognosis of colon cancer." (PMID 35118074, 2021). "In addition, chrysophanol represses cell proliferation of colon cancer via epidermal growth factor receptor (EGFR)/ mammalian target of rapamycin (mTOR) signaling proteins such as extracellular signal-regulated kinase 1/2 (ERK1/2), P70S6K and AKT." (PMID 34519612, 2021). "In addition, Akt and mTOR inhibitors can downregulate leptin-mediated PI3K/Akt/mTOR signaling which influences the colon cancer cells to proliferate and promote apoptosis." (PMID 32566099, 2020). "In conclusion, our study demonstrated that OMEO exerts anti-colon cancer activity through activation of p38 MAPK signaling, induction of protective autophagy, associated with downregulation of the mTOR/p70S6K pathway, and activation of the extrinsic and intrinsic apoptotic pathway." (PMID 32155920, 2020). "Interestingly, combinational treatment with MEK/TAK1 inhibition was earlier found to be effective in eliciting apoptosis of Kras signaling dependent colon cancer cells through inhibition of mTOR, Wnt and NF-κB signaling." (PMID 33052230, 2020). "Our data showed for the first time that OMEO significantly inhibited the proliferation of colon cancer cells, induced cytoprotective autophagy, and activated the intrinsic and extrinsic apoptotic pathway through inhibition of the mTOR/p70S6K and activation of the p38 MAPK pathway." (PMID 32155920, 2020). "Similarly, in HCT116 human colon cancer cells, perifosine inhibited Akt phosphorylation and reduced total Akt, mTOR, and p70S6K levels, resulting in the induction of apoptosis and autophagy." (PMID 32012648, 2020). "To examine the role of HIFs expression in cytotoxicity-induced cell death, we first evaluated the sensitivity of SW480 and RKO colon carcinoma cells to the chemotherapeutic drug 5-fluorouracil (5-FU), to the mTOR inhibitor CCI-779 and to the autophagy flux inhibitor HCQ." (PMID 31151160, 2019). "In addition, BEZ235, which is a dual inhibitor of PI3K and mammalian target of rapamycin (mTOR), was shown to be effective to suppress the stemness of CSCs in colon cancer by inhibiting PI3K/Akt/mTOR signaling." (PMID 35582573, 2019). "Furthermore, we identified numerous CTS transcriptional signatures whose expression was significantly associated with prognosis in colon cancer, such as CEBPB, PPARGC1, STAT3, MTOR, BCL2, JAK2, and CDK1." (PMID 31186640, 2019). "Also, the stimulation of the mTOR pathway, followed by G1-S acceleration was implicated in genomic instability and Apc LOH in a colon cancer mouse model." (PMID 31799437, 2019).